ADI1 (acireductone dioxygenase 1)
Description:
Catalyzes 2 different reactions between oxygen and the acireductone 1,2-dihydroxy-3-keto-5-methylthiopentene (DHK-MTPene) depending upon the metal bound in the active site (By similarity). Fe-containing acireductone dioxygenase (Fe-ARD) produces formate and 2-keto-4-methylthiobutyrate (KMTB), the alpha-ketoacid precursor of methionine in the methionine recycle pathway. Ni-containing acireductone dioxygenase (Ni-ARD) produces methylthiopropionate, carbon monoxide and formate, and does not lie on the methionine recycle pathway (By similarity). Also down-regulates cell migration mediated by MMP14. Necessary for hepatitis C virus replication in an otherwise non-permissive cell line.
Synonyms: ARD'; Fe-ARD; ARD; Ni-ARD; MTCBP-1; MTCBP1; HMFT1638; SIPL; APL1; FLJ10913; mtnD
Tractability: Antibody: its Gene Ontology location is reachable by antibodies, with high confidence; UniProt places it where antibodies can reach, with medium confidence. PROTAC: ubiquitination databases record sites on it; its protein half-life has been measured.
Target class: Enzyme; Oxidoreductase
Gene: Protein-coding gene on chromosome 2 (3,497,366 to 3,519,559, reverse strand). Ensembl gene ENSG00000182551.
Subcellular location: Cytoplasm; Nucleus; Cell membrane
Subcellular location (Human Protein Atlas): Nucleoplasm; Golgi apparatus
Pathways (Reactome):
Metabolism: Methionine salvage pathway
Gene Ontology:
Molecular function: acireductone dioxygenase (Ni2+-requiring) activity; acireductone dioxygenase [iron(II)-requiring] activity; oxidoreductase activity; protein binding; iron ion binding; nickel cation binding
Biological process: S-adenosylmethionine cycle; methionine metabolic process
Cellular component: cytoplasm; nucleoplasm; nucleus; plasma membrane; cytosol
Genetic constraint (gnomAD): Loss-of-function variants: 25 observed, 20.18 expected, observed/expected ratio (o/e) 1.24, 90% interval 0.9 to 1.71. The upper end of that interval is the gene's LOEUF score, 1.71, which puts it in group 6 of 6, group 1 being the genes least tolerant of losing a copy. Missense variants: 241 observed, 230.02 expected, observed/expected ratio (o/e) 1.05, 90% interval 0.94 to 1.17. Synonymous variants: 90 observed, 87.29 expected, observed/expected ratio (o/e) 1.03, 90% interval 0.87 to 1.23.
Homologues: Orthologues: chimpanzee ADI1 (99% identical), macaque ADI1 (97% identical), dog ADI1 (85% identical), rat Adi1 (85% identical), mouse Adi1 (84% identical), pig ADI1 (83% identical), rabbit ADI1 (81% identical), guinea pig ADI1 (80% identical), zebrafish adi1 (65% identical), Drosophila melanogaster Adi1 (47% identical), Caenorhabditis elegans K07E1.1 (32% identical), Caenorhabditis elegans T01D1.4 (30% identical).
Diseases named in the same sentence as ADI1 in open-access papers:
ADI1 is named in the same sentence as 51 diseases in open-access papers, as found by Europe PMC text mining. Sharing a sentence is not in itself a finding about the gene and the disease. The quoted sentences say what the papers report.
prostate carcinoma (7 papers, 2018 to 2023). A carcinoma that arises from epithelial cells of the prostate gland. "The 5′-methylthioadenosine (MTA) cycle-participating human acireductone dioxygenase 1 (ADI1) has been implicated as a tumor suppressor in prostate cancer, yet its role remains unclear in hepatocellular carcinoma (HCC)." (PMID 30858354, 2019). "Our results demonstrated that similar to the findings made in prostate cancer, wild-type ADI1 functions in modulating cell apoptosis and growth." (PMID 30858354, 2019). "ADI1, encoding acireductone dioxygenase 1, is involved in methionine salvage and prostate cancer and has no known relationship to AD." (PMID 29458411, 2018). "It is possible that the tumor suppression effect of ADI1 in HCC is mainly manifested through the MTA cycle-mediated increment of SAMe, but might not be so in prostate cancer, because the rate-limiting step for synthesis of SAMe depends on the level of methionine adenosyltransferase in cells." (PMID 30858354, 2019).
Alzheimer disease (6 papers, 2013 to 2024). A progressive, neurodegenerative disease characterized by loss of function and death of nerve cells in several areas of the brain leading to loss of cognitive function such as memory and language. "No data is available directly linking ADI1 to PD, although anecdotal evidence links ADI1 to a number of other diseases such as mitochondrial myopathy, encephalopathy, lactic acidosis, Alzheimer’s disease and stroke-like episodes." (PMID 38331996, 2024).
hepatocellular carcinoma (5 papers, 2019 to 2023). A malignant tumor that arises from hepatocytes. "Adi1 encodes 1,2-dihydroxy-3-keto-5-methylthiopentene dioxygenase that is involved in methionine salvage: 5′-methylthioadenosine cycle to increase S-adenosylmethionine levels, which altered genome-wide promoter methylation profiles, resulting in altered gene expression in hepatocellular carcinoma." (PMID 33362469, 2020). "On the one hand, ADI1 has been described as a potential tumour suppressor in hepatocellular carcinoma and prostate tumours." (PMID 35740505, 2022). "The group performed short hairpin ADI1-mediated knockdown in human hepatocellular carcinoma cell lines J7 and Huh7, showing that depletion of ADI1GP markedly enhanced cell proliferation." (PMID 34322541, 2019). "It is appealing to assume that the ability of ADI1 to induce hepatoma cell apoptosis and thus inhibit cell proliferation could be consequences of increasing productivity of MTOB or more downstream metabolites, SAMe for instance, in MTA cycle, as some studies have proposed such possibility." (PMID 30858354, 2019).
Leigh syndrome (3 papers, 2020 to 2025). A progressive neurological disease defined by specific neuropathological features associating brainstem and basal ganglia lesions. "And the other 4 genes have been associated with schizophrenia (MGAT4A), Leigh syndrome (ADI1, OMIM: 256,000), congenital hypomyelinating neuropathy (PLEKHA1, OMIM: 605,253), and ID (PCK2), respectively." (PMID 36320054, 2022).
lung adenocarcinoma (2 papers, 2023 to 2025). A carcinoma that arises from the lung and is characterized by the presence of malignant glandular epithelial cells. "The expression of ADI1 and RRP1 could be used to monitor the correct inhibition of HSP90 in lung adenocarcinoma." (PMID 37762133, 2023). "Therefore, an increased expression of ADI1, detected after inhibition of HSP90 inhibition in all molecular subtypes of lung adenocarcinoma, proved to be a potential indicator of adequate response." (PMID 37762133, 2023).
celiac disease (1 paper, 2022). An autoimmune genetic disorder with an unknown pattern of inheritance that primarily affects the digestive tract. "The most significantly up-regulated genes in celiac disease were TAP1, HLA-E, HCP5, STAT1, GBP1, STAT1, LOC100419583, and GBP4 and the down-regulated ones were IDS, PKIB, FBXO2, OXT, and ADI1." (PMID 36011206, 2022).
endometrial carcinoma (1 paper, 2022). A malignant tumor arising from the epithelium that lines the cavity of the uterine body. "Next, we analysed the ADI1 mRNA levels from the publicly available TCGA_UCEC database which contains a large cohort of data from endometrial cancer patients." (PMID 35740505, 2022). "This could be explained by the alterations in migratory and invasive capabilities that determine the overexpression of ADI1 in endometrial carcinoma cells." (PMID 35740505, 2022).
glioblastoma (1 paper, 2022). The most malignant astrocytic tumor (WHO grade IV). "On the other hand, increased ADI1 expression has been described in glioblastoma tumours and implicated in the acquisition of cellular migration capacity." (PMID 35740505, 2022).
glioma (1 paper, 2023). A benign or malignant brain and spinal cord tumor that arises from glial cells (astrocytes, oligodendrocytes, ependymal cells). "The expression levels of risk factors IL4I1, SMS, and ADI1 in high-grade gliomas were higher than those in lower‐grade gliomas, while the protein expression levels of protective factor GCLC, MSRB2, MTAP and MPST were exactly the opposite." (PMID 38057821, 2023).
hepatitis C virus infection (1 paper, 2020). A viral infection caused by the hepatitis C virus. "Methionine adenosyltransferase 2B (MAT2B) and acireductone dioxygenase 1 (ADI1), which regulate HCC development and hepatitis C virus infection, respectively, were among the top 10 HCCPMs predicted by dBMHCC." (PMID 32497121, 2020).
lung carcinoma (1 paper, 2023). "Furthermore, in our study, a higher expression of ADI1 was shown to be correlated with better disease progression outcomes and overall survival in patients with lung cancer." (PMID 37762133, 2023).
Obesity (1 paper, 2026). Accumulation of substantial excess body fat. "While discovery datasets showed high diagnostic potential, ADI1 exhibited more variable performance in obesity external validation compared to the robust consistency of ACAA1." (PMID 41801960, 2026).
serous carcinomas (1 paper, 2022). "Using public database analysis and immunohistochemistry, we established a correlation between elevated ADI1 levels and serous carcinoma." (PMID 35740505, 2022). "In addition, we found an increase in 2-Oxo-4-methylthiobutanoic acid (synthesised by the ADI1 enzyme) in serous carcinomas." (PMID 35740505, 2022).
virus infection (1 paper, 2016). "ADI1 is a downstream molecule of ENOPH1 in methionine salvage pathway and has been shown to be implicated in cell apoptosis, cell growth inhibition, oxidoreductase reaction and virus infection." (PMID 27630541, 2016). "ADI1 is a downstream protein of ENOPH1 and has been shown to play an important role in cell apoptosis, oxidoreductase reaction and virus infection." (PMID 27630541, 2016).
cancer (11 papers, 2018 to 2024). A tumor composed of atypical neoplastic, often pleomorphic cells that invade other tissues. "ADI1 expression is inversely correlated with poor prognosis and loss of ADI1 is observed in several cancer types including prostate and liver." (PMID 32824193, 2020). "Examination of the role of MTA cycle in cancer cells reproduction by mutating these critical residues in ADI1 revealed that the “on-pathway” implemented by H133 participated in the repression of HCC growth." (PMID 30858354, 2019). "Based on this evidence, and due to the reduced expression of ADI1 in different tumor types, this protein has been proposed as a possible tumor sup-pressor in several types of cancer." (PMID 37762133, 2023). "Other genes, such as CALCOCO2, RCAN2, ADI1, ECHS1, PLOD1 and VTI1B were associated with tumorigenesis or angiogenesis in some other cancers 33-35." (PMID 31632497, 2019). "This review summarizes the relationships of the MSP enzyme acireductone dioxygenase (ARD), the ADI1 gene encoding ARD and other gene products (ADI1GP) with carcinomas and carcinogenesis." (PMID 34322541, 2019). "Besides serving as a key enzyme in MTA cycle, ADI1 has been implied as a potential tumor suppressor in several types of cancers according to its declined level in cancerous tissues." (PMID 30858354, 2019). "Results indicated high expression of IL4I1, TDO2, NIT2, and IDO1, while IDO2, ADI1, DDC, HPD, BHMT2 exhibited low expression in most cancers." (PMID 38691253, 2024).
tumor (10 papers, 2013 to 2025). "The human ADI1 has been implicated as a potential tumor suppressor in numerous types of cancers." (PMID 30858354, 2019). "One proposed model suggested ADI1 represses tumor progression via physically interacting with MT1-MMP, an oncogenic protein, and thus abrogating the induced autophagy progression." (PMID 30858354, 2019). "Taken together, we demonstrated that ADI1 served as a tumor suppressor in HCC by modulating productivity of SAMe in MTA cycle." (PMID 30858354, 2019). "If ADI1 plays a tumor suppressive role in HCC, a decreased level of it when tumor progressed to a higher grade should be observed." (PMID 30858354, 2019). "Consistent with our cell-based results, it was found that the tumor volume of xenografts expressing wild-type ADI1 was significantly smaller than that in the control group." (PMID 30858354, 2019). "Similarly, the xenografts expressing the ADI1-E94A also manifested a reduced capability of tumor growth in nude mice." (PMID 30858354, 2019). "The mechanisms by which ADI1 functions as a tumor suppressor remain varied and elusive." (PMID 30858354, 2019). "Among the mechanisms by which this protein could function as a tumor suppressor is the correlation of ADI1 overexpression with a higher rate of apoptosis, which could be a consequence of the increase in metabolites produced by this enzyme in the methionine salvage pathway." (PMID 37762133, 2023). "Taken together, although we could not exclude the possibility that there might be other MTA-cycle-independent pathways involved, the present study strongly suggested that the MTA cycle and/or its downstream metabolite played a major role in ADI1-mediated tumor suppressive effect." (PMID 30858354, 2019).
ADI1 also shares sentences with these, for which no sentence is quoted: infection (12 papers); malaria (10); Leber hereditary optic neuropathy (4); leukemia (3); Immune Deficiency (2); MELAS (2); parasite infection (2); Parkinson disease (2); rheumatoid arthritis (2); acute myeloid leukemia (1); atherosclerosis (1); autoimmune disease (1); Blindness (1); cardiovascular disorder (1); cervical cancer (1); colorectal cancer (1); congenital hypomyelinating neuropathy (1); diabetes (1); Down syndrome (1); Encephalopathy (1); Fanconi anemia (1); glomerular diseases (1); hyperglycerolemia (1); lactic acidosis (1); liver cancer (1); mitochondrial disease (1); Mitochondrial myopathy (1); nervous system disorder (1); pancreatic cancer (1); pancreatic tumor (1).
A further 5 diseases each share a sentence with ADI1 in 1 paper.